NANOG (Nanog homeobox)
Diseases named in the same sentence as NANOG in open-access papers (continued):
Sharing a sentence is not in itself a finding about the gene and the disease.
germ cell tumor (14 papers, 2006 to 2024). A benign or malignant, gonadal or extragonadal neoplasm that originates from germ cells. "Proteins were closely linked to proteins such as SOX-2, SOX-17, NANOG, or OCT3/4, which all have been described to play crucial roles in pluripotency and differentiation of germ cells and germ cell tumors." (PMID 31565104, 2019). "Recently, our group and others demonstrated that lineage-restricted transcription factors such as OCT4 and NANOG are robust markers for the diagnosis of germ cell tumors, including those in the central nervous system." (PMID 19936203, 2009). "By contrast, some reports have indicated that germ cell tumors in human testes ectopically express NANOG." (PMID 16859545, 2006). "Moreover, tectorigenin lowered the expression of the stem cell factors POU5F1 and NANOG, and inhibited the proliferation of malignant testicular germ cell tumor (TGCT) cells." (PMID 37570873, 2023). "Interestingly, while in germ cell tumors, NANOG is a relevant transcript, in prostate tumors, KLF4 is a relevant stem marker." (PMID 27901106, 2016). "NANOG has also been found to be a sensitive and specific marker of metastatic germ cell tumors." (PMID 25120646, 2014). "NANOG can be used to distinguish between germ cell tumors and non-germ cell tumors." (PMID 25120646, 2014). "Non-germ cell tumors, including breast and oral cancer, also express NANOG." (PMID 25120646, 2014). "In the current study, NANOG protein expression was positive in 92.8% (n=26/28) of OSCC cases, all of which were primarily observed in the cytoplasm of tumor cells, whereas in germ cell tumors, a nuclear staining pattern was seen." (PMID 38558704, 2024). "Immunohistochemical analysis of NANOG expression showed positive staining in a large proportion of OSCC cases, with a cytoplasmic pattern, in contrast to the nuclear pattern observed in germ cell tumors." (PMID 32733958, 2020). "Comparative transcriptome analysis using the cancer genome atlas (TCGA) data reveals a positive correlation between NANOG and HSP90AA1 mRNA levels in multiple human cancer types, such as cholangiocarcinoma, testicular germ cell tumors, uveal melanoma." (PMID 31992715, 2020). "We found a correlation between PIM1/2 expression and VENTX, SOX15, UTF1, NANOG, POU5F1P4, POU5F1P3, and POU5F1B expression in male germ cell tumors." (PMID 27901106, 2016). "Moreover, we confirmed that LTR5_Hs were preferentially bound by KLF4, NANOG, POU5F1, and TFAP2C in naïve ESCs, by TFAP2C in PGCLCs, and by SOX17 in a germ cell tumor cell line using publicly available ChIP-Seq datasets." (PMID 35551519, 2022). "Another study has detected NANOG in human fetal gonocytes, testicular carcinoma in situ and germ cell tumours, but not in normal adult testis." (PMID 20539761, 2010). "Notably, elevated NANOG protein expression in several types of human cancer has been reported, predominantly in germ cell tumors, as well as the malignancies of non-germ cells, suggesting the involvement of NANOG in tumorigenesis and progression." (PMID 25120646, 2014).
sarcoma (14 papers, 2012 to 2025). A usually aggressive malignant neoplasm of the soft tissue or bone. "In this study, we investigated the role of stemness markers in DSRCT survival and metastasis, finding that elevated levels of SOX2 and NANOG are associated with worse survival in sarcoma patients and are elevated in metastatic DSRCT tumors." (PMID 36506091, 2022). "The predicted influence of MYC and NANOG is particularly relevant, as these TFs are central players in oncogenic reprogramming and have been shown to mediate stem-like phenotypes in various sarcomas and solid tumors." (PMID 41303462, 2025). "It is reported that NANOG is upregulated in sarcoma CSCs and promotes the formation of sarcoma cells, making it resistant to chemotherapy and radiotherapy, and this resistance can be overcome by inhibiting NANOG." (PMID 38561775, 2024). "Mechanistically, we found that Ebf1-KRAB-expressing sarcoma cells exhibit a reduced enrichment of EWS/ATF1 at the super-enhancer when compared with the control NANOG-KRAB-expressing sarcoma cells." (PMID 31488818, 2019). "Consistently, Cdkn1a and Ink4a, as well as Il-6, were upregulated in Ebf1-KRAB-expressing sarcoma cells when compared with control NANOG-KRAB-expressing sarcoma cells." (PMID 31488818, 2019). "FOXM1 stimulates transcription of pluripotency related genes including SOX2, KLF4, OCT4, and NANOG many of which are important in sarcoma, a disorder of mesenchymal stem cell/ partially committed progenitor cells." (PMID 27074562, 2016). "A recent study of Oct-4 and NANOG in OS demonstrated that the two markers were highly expressed in CSCs, which suggests that these transcription factors play a role in sarcoma stem cell biology." (PMID 23181114, 2012). "In addition, it is reported that inhibiting AKT1/2 reduces NANOG expression in sarcoma CSC to reverse chemotherapy resistance, NANOG mediates the radio-resistance of tumor cells through AKT and Notch pathways partially." (PMID 38561775, 2024). "Recently, the presence of increased ALDH1 activity allowed the identification of a subpopulation of human sarcoma cell lines with stem cell properties, including high level of expression of stem cell genes such as NANOG, OCT3/4, STAT3 and SOX2, and resistance to chemotherapy." (PMID 23734203, 2013). "With the expression of pluripotency factors such as OCT3/4, NANOG, KLF4 and SOX2, stemness in sarcoma is a variable condition." (PMID 37635229, 2023). "Lower levels of sarcoma CSC markers SOX2, NANOG, ALDH1A1, ABCB1 and ABCC1 were observed in silenced cells in 2D and in CSC-enriched cultures (single-cell and 3D/spheroid)." (PMID 35864381, 2022). "In summary, our work shows that EMX1 and EMX2 act as tumor suppressors by suppressing the activity of stem cell regulatory genes (OSKM, NANOG, and PROM1) and effectors of the canonical Wnt pathway (CTNNB1, TCF4, MYC, WNT1 and CCDN1) in sarcoma." (PMID 34364391, 2021). "In summary, our work showed that EMX1 and EMX2 act as tumor suppressors by suppressing the activity of stem cell regulatory genes (OCT4, KLF4, MYC, SOX2, NANOG, NES, and PROM1) in sarcoma." (PMID 34016958, 2021). "NANOG is important for CSC maintenance, as it regulates the expression of other stem cell markers OCT4, SOX2, KLF4, and promotes sarcoma CSC features such as spheroid formation, anchorage-independent growth, migration and invasion." (PMID 35145908, 2021). "Our work showed that EMX1/EMX2 act as tumor suppressors in sarcomas by repressing the activity of stem cell regulatory genes (OCT4, SOX2, KLF4, MYC, NANOG, NES, and PROM1)." (PMID 34016958, 2021). "The stemness state in sarcomas is orchestrated by the expression of pluripotency factors such as OCT3/4, NANOG, KLF4, and SOX2." (PMID 32295077, 2020). "Survival analysis revealed that higher expression of SOX2, NANOG, and MYC but not OCT4 (POU5F1) or KLF4 is associated with significantly reduced survival in sarcoma patients." (PMID 36506091, 2022).
sarcoma (continued). "Besides, CSC and drug-resistance related genes in sarcoma such as SOX2, NANOG, ALDH1A1, ABCB1 and ABCC1 were down-regulated in 2D, as well as in CSC-enriched cultures (colony-forming and 3D/ spheroid)." (PMID 35864381, 2022).
squamous cell carcinoma (14 papers, 2015 to 2023). A carcinoma arising from squamous epithelial cells. "There was a statistically significant difference between the relative mRNA expression of SOX2 and NANOG in adenocarcinoma compared to squamous cell carcinoma." (PMID 31921651, 2019). "A similar, but more significant increase in the number of cancer stemness genes was also found in squamous cell carcinoma patients, NANOG (p<0.01), OCT-4 (p<0.05), SOX-2 (p<0.01), C-MYC (p<0.05)." (PMID 29069808, 2017). "We recently reported that NANOG is frequently aberrantly expressed in squamous cell carcinomas, including HNSCC5." (PMID 28894270, 2017). "NANOG is a key pluripotency factor in embryonic stem cells that is frequently expressed in squamous cell carcinomas (SCCs)." (PMID 25988972, 2015). "Of relevance, SOX2, OCT4 and NANOG are also particularly involved in squamous cell carcinoma malignization and progression." (PMID 26203771, 2015). "Other markers such as cortactin, NANOG, and SOX2 protein expression are frequent in squamous cell carcinoma." (PMID 36980171, 2023). "In contrast, PDPN expression, a demonstrated CSC marker in squamous carcinoma cells, while showing similar relationships with different TILs subtypes such as SOX2 and NANOG, was only significantly correlated with stromal and tumoral FOXP3+ cells." (PMID 34201050, 2021). "Together, our results unravel a novel function of NANOG in promoting EMT and malignancy in squamous cell carcinomas." (PMID 25988972, 2015). "NANOG, OCT4, and SOX2 mRNA expressions have previously been shown to be significantly higher in samples of moderately and poorly differentiated compared to well-differentiated squamous cell carcinoma." (PMID 32733958, 2020). "However, the opposite result was obtained for squamous cell carcinoma, in which lower SOX2 and NANOG expression was found in ALDHhigh cells than in ALDHlow cells." (PMID 31921651, 2019). "In the present study, we showed that overexpression of BRACHYURY upregulated NANOG expression slightly, but failed to promote self-renewal capacity not only in ACCS GFP (adenoid cystic carcinoma) cells but also in TF GFP, a squamous cell carcinoma cell line." (PMID 30453543, 2018).
oral cancer (12 papers, 2014 to 2025). "Positive NANOG expression associated with progression to oral cancer-positive expression of both markers demonstrated higher risk." (PMID 35326482, 2022). "Univariate Kaplan–Meier and Cox analysis also showed that cytoplasmic NANOG, nuclear NANOG, and the histological grade of dysplasia were significantly associated with oral cancer risk (p = 0.002, p = 0.001 and p < 0.001, respectively)." (PMID 31484317, 2019). "Remarkably, our findings uncover the potential application of NANOG expression as an early predictor of oral cancer risk in patients with oral potentially malignant disorders." (PMID 31484317, 2019). "NANOG expression emerges as an early predictor of oral cancer risk in patients with OPMD." (PMID 31484317, 2019). "In addition, patients harboring NANOG–positive dysplasias either considering cytoplasmic or nuclear NANOG expression were consistently and significantly associated with an increased risk of progression to oral cancer (p = 0.02 and p = 0.04, respectively)." (PMID 31484317, 2019). "Cytoplasmic NANOG expression and the histopathological grading were significantly correlated with oral cancer risk, although dysplasia grading was the only significant independent predictor of oral cancer development in multivariate analyses." (PMID 31484317, 2019). "Therefore, decoding the molecular mechanisms of NANOG regulation can help in developing new therapeutic strategies for oral cancer." (PMID 38558704, 2024). "Therefore, decoding the molecular mechanisms of NANOG regulation in the progression of cancer helps in developing new therapeutic strategies for oral cancer." (PMID 38558704, 2024). "Additionally, after a mean follow-up of 185 months, patients who harbored NANOG-positive cells showed significantly higher chances for malignant progression to oral cancer." (PMID 38558704, 2024). "This review illustrates the interplay between miRNA and various known TF of oral cancer such as c-Myc, SOX, STAT, NANOG and OCT in orchestrating the stemness and resistance features." (PMID 38170015, 2023). "Using the GSE26549 oral cancer cohort (n = 49), we also demonstrated mild or strong positive correlations between TRPM7 and NANOG (r = 0.214, p = 0.048) or BMI-1 (r = 0.628, p < 0.001)." (PMID 35771152, 2022).
osteosarcoma (12 papers, 2012 to 2025). A usually aggressive malignant bone-forming mesenchymal neoplasm, predominantly affecting adolescents and young adults. "More recently, several studies demonstrated that expression of ESC transcription factors in osteosarcoma cells, specially NANOG, is decreased by compounds such as dimethylaminomicheliolide, ethanoic C. cassia extracts, and also the anesthetic levobupivacaine." (PMID 37176108, 2023). "EID3 overexpression not only improved stem cell phenotype but also enhanced the enrichment of CD133+ cells and the expression of stem cell-related markers OCT3/4, ABCG2, and NANOG in osteosarcoma cells." (PMID 36071872, 2022). "Out of the differentially modulated genes, those implicated in stem cell and osteosarcoma biology, such as PPARG, ETS1, WNT1, WNT5B, SOX2, NANOG, POU5F1, nestin, and ALDH were chosen for further analysis." (PMID 22870217, 2012). "Decitabine exposure in osteosarcoma reduces the protein expression of the metastasis-associated markers VIMENTIN, SLUG, ZEB1, and MMP9, with a concurrent decrease in mRNA expression of the known stem cell markers SOX2, OCT4, and NANOG." (PMID 37197432, 2023). "Therefore, identification of TSCs based on POU5F1, SOX2, or NANOG expression remains controversial, at least in osteosarcoma." (PMID 22870217, 2012). "Meanwhile, osteosarcoma cells with overexpressed TBL1XR1 had higher expression of stemness markers including ABCG2, BMI1, SOX2, NANOG, and OCT4, indicating that TBL1XR1 endowed osteosarcoma cells with stem cell-like properties." (PMID 38347836, 2024). "Our RT-qPCR data revealed that mRNA levels of stemness-related markers, such as NANOG, SOX2, CD44, and CD133, were significantly downregulated in JAGGED1-silenced osteosarcoma cells." (PMID 34725550, 2021). "The contribution of NANOG and ABCG2 in patient-derived osteosarcoma cells resistance to methotrexate still needs to be clarified." (PMID 28934267, 2017).
breast tumor (11 papers, 2012 to 2024). "In our second approach, Kaplan-Meier survival curve revealed lower probability of overall survival (OS) in breast tumor patients with higher CSC (NANOG) (p < 0.05) and Treg (FOXP3) (p < 0.05) signature genes, in concordance with earlier reports." (PMID 38038865, 2023). "To test this idea, we overexpressed or reduced KLF8 expression in MDA-MB-231 and SUM159 cells and assessed mRNA and protein expression of major stem cell factors that are associated with breast tumor development and include OCT4, SOX2, NANOG and c-MYC." (PMID 37152043, 2023). "Previous work has demonstrated expression of OCT4, SOX2, and NANOG in some breast tumors, particularly triple negative cancers that are poorly differentiated and have poor prognosis." (PMID 23596564, 2013). "Consistent with our findings in the mouse, siRNA studies have demonstrated that OCT4 and NANOG expression are required for human breast tumor-initiating activity." (PMID 22992387, 2012). "Given that increased stem cell biomarker expression was observed in high NOS2 expressing ER- breast tumors, we measured CSC biomarker expressions (ALDH1A1, OCT4, CXCR4, CD133, CD117, CD44 and NANOG) in the control and DETANO treated MCF10A cells." (PMID 36830680, 2023). "We have recently shown that the embryonic stem cell markers NANOG, OCT4 and SOX2 are expressed in normal breast stem cells and at higher levels in breast tumour cells and that their expression is reduced during cell differentiation." (PMID 24178749, 2014). "A unifying feature between the normal lactating breast and the examined breast tumors was upregulation of OCT4, which was co-localized with NANOG in the majority of positive cells." (PMID 23596564, 2013). "Furthermore, the expression of OCT4, but not PRDM14, SOX2, REX1 or NANOG was higher in breast tumor and metastasis samples, suggesting negative regulation of Xist by OCT4." (PMID 27248326, 2016). "Moreover, we observed and calculated the number of OCT4/SOX2/NANOG/FOXP3 positive cells per area taken from sections of the tumor tissues, and consequently found similar trend in stemness genes and FOXP3 coincides with high-grade of breast tumor compared to low-grade breast tumor (p < 0.0001)." (PMID 38038865, 2023). "The existing body of research on SOX‐2, OCT‐4 and NANOG suggests that early‐stage breast tumors exhibit SOX‐2 expression, with no expression of OCT‐4 and NANOG." (PMID 34914196, 2022).